CXCL5 (C-X-C motif chemokine ligand 5)
Diseases named in the same sentence as CXCL5 in open-access papers (continued):
Sharing a sentence is not in itself a finding about the gene and the disease.
prostate carcinoma (31 papers, 2009 to 2026). A carcinoma that arises from epithelial cells of the prostate gland. "However, other studies found that CXCL5 is overexpressed in various types of cancers, including prostate cancer, and is associated with tumor progression." (PMID 39765818, 2024). "The results of the present study showed that CXCL5 enhanced cancer cell growth in vitro and in xenograft animal studies, a finding which agrees with other studies that have found CXCL5 to be associated with tumor progression in prostate cancer." (PMID 39765818, 2024). "In this study, our objective is to elucidate the function of CXCL5 in human prostate cancer and stromal cells and to investigate the antioxidant characteristics of the CXCL5/CXCR2/HO-1 axis in human prostate cells." (PMID 39765818, 2024). "CXCL5 secreted from prostate cancer cells enhanced neutrophil migration, indicating the chemotactic characteristics of CXCL5 in prostate cancer cells." (PMID 39765818, 2024). "The present study is the first to determine the effect of CXCL5 on the expression of the HO-1 gene and its modulation of ROS in prostate cancer and myofibroblast cells." (PMID 39765818, 2024). "In particular, prostate-specific antigen (PSA) and CXCL5 levels are known to increase in the serum of prostate cancer patients." (PMID 39765818, 2024). "A recent study revealed that stroma CXCL5 is involved in prostate cancer progression and metastasis." (PMID 39765818, 2024). "To support our concept that CXCL5 is an oncogene in human prostate cancer cells, we constructed a CXCL5-overexpressed LNCaP cell line." (PMID 39765818, 2024). "The chemotactic characteristics of CXCL5, which induce neutrophil migration to affect tumorigenesis, are well-known in several cancers, including prostate cancer." (PMID 39765818, 2024). "CXCL5 induced cell proliferation and invasion of prostate cancer cells in vitro and tumorigenesis in a xenograft animal model." (PMID 39765818, 2024). "In this study, we profiled the cytokine-chemokine serum levels associated with prostate cancer and demonstrated that serum chemokines CXCL2, CXCL5, and CCL23 are the most distinguished chemokines differentially expressed in men of AA and CA races." (PMID 37698493, 2023). "Due to increased circulatory CXCL2 and CXCL5 levels, AA men likely acquire a disadvantage with vulnerable immune surveillance, leading to aggressive prostate cancer, as often seen in AA men at diagnosis." (PMID 37698493, 2023). "GNA13 (α subunit of a heterotrimeric G-protein), which can stimulate expression of CXCL5 via NF-κB pathway, becomes a novel therapeutic target due to the effect of this chemokine on prostate cancer." (PMID 37393391, 2023). "Elevated CXCL5 protein expression in primary and metastatic prostate tumors aligned with prostate cancer promotion and metastasis, driving cell migration and EMT-transition in hormone-refractory prostate cancer cells." (PMID 37698493, 2023). "For example, increased secretion of CXCL5 in prostate cancers is known to recruit MDSCs and Treg cells to the tumor microenvironment, which blocks cytotoxic T cell activity and protects tumor cells from T cell-mediated cell death." (PMID 34689178, 2022). "Another study pointed out that apoptosis-mediated CXCL5 hastens inflammation and osseous metastasis of prostate cancer." (PMID 35936390, 2022). "Collectively, our results illustrate that MALT1 modulates the expressions of IL-6 and CXCL5 via NF-κB activation, thereby contributing to tumor progression and malignancy in prostate carcinoma cells." (PMID 33802402, 2021). "MALT1 facilitated NF-κB subunits (p50 and p65) nuclear translocation to induce gene expression of interleukin 6 (IL-6) and C-X-C motif chemokine 5 (CXCL5) in prostate carcinoma cells." (PMID 33802402, 2021).
prostate carcinoma (continued). "CXCL5 has been reported to be of great value in mediating inflammation and tumor growth in patients with bone metastasis in prostate cancer." (PMID 31897234, 2020). "CXCL5 secreted from prostate cancer cells attracts MDSCs expressing CXCR2 in a mouse model of prostate cancer." (PMID 30736371, 2019). "Since in vitro cell models and animal studies have found that CXCL5 blocked HO-1 expression, we continued on to determine whether CXCL5 has antioxidant capacity in human prostate cancer cells." (PMID 39765818, 2024). "Further investigation of PTEN on CXCL5 expression in prostate cancer cells is warranted." (PMID 39765818, 2024). "CXCL5 secreted from prostate cancer cells enhanced neutrophil migration." (PMID 39765818, 2024). "In addition, the CXCL5/CXCR2 axis has been implicated in cancers, in which it can facilitate tumor progression and metastasis, including prostate cancer." (PMID 39765818, 2024). "Lower levels of CCL23 in AA prostate cancer patient sera and tumor tissues and high CXCL2 and CXCL5 may contribute to aggressive prostate cancer, as often seen in AA men." (PMID 37698493, 2023). "CXCL5 can also promote prostate cancer cell colony formation, proliferation, and migration." (PMID 35936390, 2022). "Previous studies indicated that IL-6 and CXCL5 could induce androgen-independent prostate cancer progression." (PMID 33802402, 2021). "Our results showed that CXCL5 was a prognostic gene, suggesting that the inflammatory mediator, CXCL5, might be a potentially protective prognostic factor for prostate cancer." (PMID 34133324, 2021). "For example, the prostate cancer metastasis-promoting role of CXCL5 has been recently shown." (PMID 34209195, 2021). "A recent study demonstrated that efferocytosis of apoptotic cancer cells activates NF-κB and STAT3 transcriptional machinery to promote the production of the pro-inflammatory C-X-C motif chemokine 5 (CXCL5) in the bone microenvironment, which supported prostate cancer skeletal metastasis." (PMID 32326073, 2020). "This study explored the concept that CXCL5 is an antioxidant oncogene through the CXCL5/CXCR2/HO-1 pathway in prostate cancer cells, suggesting that the CXCL5/CXCR2/HO-1 signaling pathway could provide a new strategy for the treatment of oxidative stress in the prostate." (PMID 39765818, 2024). "Furthermore, treatment with the CXCR2 inhibitor SB225002 blocked HO-1 expression and upregulated endogenous ROS and H2O2-induced ROS levels in prostate cancer cells, indicating that CXCL5 affects endogenous ROS and H2O2-induced ROS, and is dependent on HO-1 and CXCR2." (PMID 39765818, 2024). "Serum levels of CXCL2 and CXCL5 exhibited race-specific differences, while CCL23 showed both race- and cancer-specific differences supporting the potential contribution of systemic chemokines in differential outcomes among races in association with prostate cancer." (PMID 37698493, 2023). "Thus, the loss of DARC may be a potential trade-off in protecting against the malarial parasite with an increased level of inflammatory chemokine CXCL5 suppressing antitumor immunity and promoting aggressive prostate cancer in AA men." (PMID 37698493, 2023). "However, CXCL5 was also recently shown to promote prostate cancer progression." (PMID 20027305, 2009). "In prostate cancer, the expression of forkhead box F2 (FOXF2) in the stroma correlates with CXCL5 levels, and reduced CXCL5 enhances FOXF2 expression, leading to increased T cell infiltration." (PMID 40038745, 2025). "CXCL5 modulates the cell cycle and EMT to induce cell proliferation and invasion of prostate cancer cells in vitro and tumor growth in xenograft animal models." (PMID 39765818, 2024).
prostate carcinoma (continued). "Although TRAIL can stimulate the expression of prometastatic molecules like CXCL5/ENA-78 and IL-6 in prostate cancer cells, this effect can be countered using an AKT inhibitor combined with TRAIL." (PMID 39416732, 2024). "Selected chemokines (CXCL2, CXCL5, and CCL23) serum level was validated in 211 serum samples from prostate cancer patients and healthy controls." (PMID 37698493, 2023). "For example, we showed that the expression of CXCL6 and CXCL8, the functional homologs of mouse Cxcl5, are both inversely correlated with that of FOXF2 in human prostate cancer specimens." (PMID 36369237, 2022). "We further confirmed that Cxcl5 was downregulated, and Cxcl9/10 were upregulated in the FACS-isolated stromal cells from both RM-1 xenografts and prostate cancer tissues of Col1a2-Foxf2-TRAMP mice as compared to their respective controls." (PMID 36369237, 2022). "We found that rTRAIL and sTRAIL induced CXCL5/ENA-78 and IL-6 expression in TRAIL-resistant prostate cancer cells." (PMID 31010082, 2019). "CXCL5 evinces antioxidant properties by upregulating heme oxygenase-1 (HO-1) to counteract H2O2-induced reactive oxygen species (ROS) in a CXCR2-dependent manner in WPMY-1 and prostate cancer cells." (PMID 39765818, 2024). "That may explain why DU145 cells, an aggressive cell line, expressed extremely low levels of CXCL5 in this study; namely, DU145 cells are PTEN-positive prostate cancer cells." (PMID 39765818, 2024). "Except for the well-known anti-inflammatory oncogene, there has been no report indicating the antioxidant characteristics of CXCL5 in prostate cancer; however, a recent study illustrated CXCL5 as having antioxidation characteristics in mouse adipocytes." (PMID 39765818, 2024). "In summary, the elevated serum chemokines CXCL2 and CXCL5, in conjunction with a low level of CCL23, may contribute towards suppressed antitumor immunity and account for lethal prostate cancer in AA men." (PMID 37698493, 2023). "In contrast, race-specific differences were observed for significantly higher serum levels of CXCL2 (p < 0.0001), CXCL5 (p = 0.016), and IL-6 (p = 0.004), and lower levels of CCL23 (p < 0.0001) and CCL27 (p = 0.016) in AA prostate cancer patients (n = 14) compared to CA (n = 14)." (PMID 37698493, 2023). "The activation of MALT1 on the expressions and secretions of IL-6 and CXCL5 was blocked under the treatment of MI-2 or CAPE, suggesting that upregulation of MALT1 on the IL-6 and CXCL5 expressions may rely on the MALT1/NF-κB pathway in prostate carcinoma cells." (PMID 33802402, 2021).
Obesity (30 papers, 2009 to 2026). Accumulation of substantial excess body fat. "For instance, the expression of CCL5 and CCL20 has been associated with fatty liver disease, while CXCL5 is an adipose tissue derived factor associated with obesity." (PMID 32764789, 2020). "Similar to TNFa, elevated levels of CXCL5 in serum have been observed in obese mouse models, and CXCL5 is associated with the onset of obesity and hyperglycemia in serum panel measurements." (PMID 27603698, 2016). "In addition to the role of CXCL5 in anti-infection, cancer, and obesity, CXCL5 is associated with inflammatory diseases such as acute respiratory distress syndrome and arthritis through proinflammatory effects." (PMID 37569554, 2023). "CXCL5 has been directly implicated in obesity and insulin resistance." (PMID 32424099, 2020). "Also, they showed a significant positive correlation between serum level of CXCL5 and body weight in the French population and reported that inhibition of CXCL5 secretion in obese people can reduce the risk of developing obesity-related pathogenesis." (PMID 29387827, 2017). "Since CXCL5 is an inflammatory factor, and sinceits levels are increased in obese patients, we could speculate that CXCL5 is atthe origin of obesity- associated co-morbidities." (PMID 20157549, 2009). "The roles of CXCL5 in obesity may involve causing inflammation and mediating insulin resistance." (PMID 34537202, 2021). "Abrogation of the signal pathways of CXCL14, CXCL5, CCL2, or their cognate chemokine receptors, alleviated obesity-associated metabolic abnormalities in high fat diet (HFD)-induced obese mice." (PMID 34948325, 2021). "CXCL5 is a proinflammatory chemokine that promotes insulin resistance and is secreted from white adipose tissue in excess in obesity." (PMID 33716989, 2021). "In the serum of diabetic-induced db/db mice and obesity-induced ob/ob mice, the CXCL5 concentration was two times higher than that in lean mice." (PMID 34537202, 2021). "CXCL5 is known to be an inflammatory cytokine that is highly secreted in the conditions of obesity, diabetes, and infection." (PMID 34537202, 2021). "CXC Ligand 5 (CXCL5) is a new cytokine which is secreted from white adipose tissue during obesity and by blocking insulin signaling pathway inhibits the activity of insulin and promotes insulin resistance." (PMID 29387827, 2017). "Previous studies have shown that serum level of CXCL5 is highly increased during obesity in both mice and humans." (PMID 29387827, 2017). "CXC Ligand 5 (CXCL5) is a new cytokine which inhibits the activity of insulin in muscles and promotes insulin resistance and secreted from white adipose tissue during obesity." (PMID 29387827, 2017). "Aberrant CXCL5 levels have been detected in various acute and chronic diseases, such as microbial infections, rheumatoid arthritis, obesity, and inflammatory bowel diseases." (PMID 26738635, 2016). "Aberrant CXCL5 levels have been detected in various acute and chronic diseases including microbial infections, rheumatoid arthritis, obesity, chronic pancreatitis, inflammatory bowel diseases, sun burn (UV), and several cancers." (PMID 24695525, 2014). "Recently, it has been shown that circulating CXCL5 is highly increased during obesity in mice and that CXCL5 can induce insulin resistance." (PMID 23991422, 2013). "In our paper weshow that CXCL5 is a new chemokine secreted by adipose tissue residentmacrophages and that circulating CXCL5 is highly increased during obesity inboth mice and humans." (PMID 20157549, 2009). "In this context, it isinteresting the recently suggested correlation between obesity and asthma.Strikingly, exacerbation of asthma has been also correlated with increasedexpression of both CXCL5 and its receptor CXCR2." (PMID 20157549, 2009). "Additionally, During the development of obesity-related diseases, chemokines such as CXCL5 and CXCL8, secreted by white adipose tissue, are highly expressed in the adipose tissue of obese subjects." (PMID 39334887, 2024).
Obesity (continued). "The functional enrichment analysis of the DEGs showed clustering around the genes CXCL5, EGF, and SPARC, which are associated with diabetes, obesity, and insulin secretion and enriched in disease ontology terms of metabolic disease, diabetes, and glucose metabolism disease." (PMID 36138412, 2022). "Interestingly, CXCL5 drives obesity to diabetes and our mice on HFD started to exhibit elevated glucose levels." (PMID 33673387, 2021). "Furthermore, a high CXCL5 concentration in serum is known to affect obesity, hyperglycemia, and islet function." (PMID 34537202, 2021). "Circulating CXCL5 is highly increased during obesity in both mice and humans." (PMID 29387827, 2017). "Interestingly, CXCL5/RANTES is up-regulated in adipose cells in response to obesity and thus has been suggested as one of the main chemokines responsible for the consequent T cell infiltration." (PMID 25333488, 2014). "CXCL5 is an adipose tissue derived factor that links obesity with insulin resistance." (PMID 22292925, 2012). "Taken together, theseobservations suggest that the increased CXCL5 circulating levels observedduring obesity could contribute to the development or progression of IBD." (PMID 20157549, 2009). "Inhibiting CXCL5 secretion or function in obese individualsnot only ameliorate their insulin sensitivity, but could also decrease the riskof developing other major obesity-related pathologies." (PMID 20157549, 2009). "However, upon adjusting for obesity, CXCL5 and LEP were attenuated indicating that their expressions may be mediated by obesity." (PMID 41507467, 2026). "Thus, although a number of studies have shown the involvement of CXCL5 in metabolic disease, the precise role of CXCL5 in obesity-related diseases remains unclear." (PMID 34537202, 2021). "Thus, the serum level of CXCL5 increases with weight gain and obesity." (PMID 29387827, 2017). "However, CXCL1 and CXCL5 were increased significantly in serum at the onset of obesity and T2D." (PMID 27843953, 2016). "Finally, but not limited to, CXCL5 couldbe also involved in the development of obesity-related inflammatory boweldisease." (PMID 20157549, 2009). "A study reported a subsequent decrease in serum CXCL5, HOMA-IR, and TNFα levels in sedentary women with obesity after a 12-week exercise training program." (PMID 39334887, 2024). "Other chemokines involved in AT macrophage infiltration and obesity-induced IR are CCL5, C-X-C motif chemokine ligand 5 (CXCL5), and CXCL14." (PMID 33671547, 2021). "Another possibility being the dependence of neutrophil chemotaxis on CXCL5 (LIX), binding both CXCR1 and CXCR2, which levels are also increased in obesity." (PMID 33673387, 2021). "Recent data have shown that, along with CXCL5, circulating levels of CXCL1, with high affinity to CXCR2, are markedly increased in the db/db mice and correlate with obesity development." (PMID 34571976, 2021). "Besides CCL2/MCP-1, several other chemokines such as CCL5, C-X-C motif chemokine ligand 5 (CXCL5) and CXCL14 are also involved in adipose tissue macrophage infiltration and obesity-induced insulin resistance." (PMID 24733068, 2014). "Since microglial activation as well as Cxcl5 mRNA level was consistently lower in the hypothalamus of Pdgfrb∆SYS-KO than in FL, free fatty acids may also contribute to pericyte-mediated hypothalamic inflammation in obesity." (PMID 38317079, 2024). "In addition, many other cytokines and chemokines are increased in obesity including leptin, resistin, IL-7, IL-8, retinol binding protein- (RBP-) 4, plasminogen activator inhibitor- (PAI-) 1, chemokine- (C-X-C motif-) ligand 5 (CXCL5), visfatin, chemerin, and vaspin." (PMID 27843953, 2016).